GAS7 (growth arrest specific 7)
Diseases named in the same sentence as GAS7 in open-access papers (continued):
Sharing a sentence is not in itself a finding about the gene and the disease.
breast tumor (2 papers, 2014 to 2018). "We found significantly lower GAS7b mRNA expression level in the lymph-node metastatic tumors compared to their paired primary tumor samples, For IHC analysis, we used commercial tissue array to analyze GAS7 protein expression in clinical breast tumor samples." (PMID 29706651, 2018).
colorectal cancer (2 papers, 2013 to 2020). A primary or metastatic malignant neoplasm that affects the colon or rectum. "Methylation profiles in colorectal cancer (CRC) showed 50 significantly hypermethylated CpG sites located within six genes in African American patients, including GAS7 gene." (PMID 32605309, 2020). "Additionally low expression of GAS7 has been reported in lung squamous cell carcinoma suggesting its importance as marker, but this gene has not been previously found to be methylated in LUAD but reported as methylated in colorectal cancer." (PMID 24369052, 2013).
leiomyoma (2 papers, 2007). A well-circumscribed benign smooth muscle neoplasm characterized by the presence of spindle cells with cigar-shaped nuclei, interlacing fascicles, and a whorled pattern. "They included several genes such as NR2F1, PNN, Smad4, Smad5, STAT5B, JUN, TGIF2, and ATF1 that were over-expressed while RUNX3, STAT1, STAT6, EGR3, GAS7, Smad1, and EDF1 were underexpressed in leiomyomas as compared to keloid/incisional scars." (PMID 17718906, 2007). "A balance between cell growth and apoptosis is critical in progression of tissue fibrosis and the expression of several genes functionally related to these categories, including Bcl-XL, Bad, Bax, p27Kip1, p57Kip2, Gas1, Gas7, CST6, CST7, caspases, etc., were identified in leiomyomas and myometrium." (PMID 17716379, 2007).
non-small cell lung carcinoma (2 papers, 2015 to 2023). A group of at least three distinct histological types of lung cancer, including non-small cell squamous cell carcinoma, adenocarcinoma, and large cell carcinoma. "Notably, GAS7 deficiency was implicated in miR-181a-mediated gefitinib resistance in non-small-cell lung cancer." (PMID 36908025, 2023). "We further performed a prognosis analyses in relation to GAS7 mRNA expression using publicly available microarray data of non-small cell lung cancer samples from TCGA (The Cancer Genome Atlas)." (PMID 26506240, 2015). "In addition, miR-181a-mediated down-regulation of GAS7 contributed to gefitinib resistance in non-small cell lung cancer." (PMID 36908025, 2023).
Obesity (2 papers, 2013 to 2019). Accumulation of substantial excess body fat. "Downregulation of the growth arrest-specific gene 7 (GAS7) has been associated with chronic inflammation and obesity." (PMID 31969876, 2019).
SAPHO syndrome (2 papers, 2019 to 2021). SAPHO syndrome (acronym for Synovitis, Acne, Pustulosis, Hyperostosis and Osteitis) is an auto-inflammatory disease, mainly characterized by the association of neutrophilic cutaneous involvement and chronic osteomyelitis. "The ROC curve of GAS7 and Lnc-CLLU1.1-1:2 indicated that such pair may be a promising biomarker of SAPHO syndrome." (PMID 34234815, 2021). "However, the mechanism how GAS7 and Lnc-CLLU1.1-1:2 participate in the etiology and development of SAPHO syndrome requires further investigation." (PMID 34234815, 2021). "In the meanwhile, growth-arrest-specific 7 gene (GAS7) is required for osteoblast differentiation, which may play a role in bone manifestations in SAPHO syndrome." (PMID 31395074, 2019).
B-cell acute lymphoblastic leukaemia (1 paper, 2011). "The growth arrest-specific 7, Gas7, is regulated by Sox9 and the ERK1/2 MAP kinase and is involved in chondrogenesis, and has been reported to form a MLL/GAS7 fusion protein in a pediatric case of B-cell acute lymphoblastic leukaemia." (PMID 21492432, 2011).
chronic kidney disease (1 paper, 2022). Impairment of the renal function secondary to chronic kidney damage persisting for three or more months. "Seventeen-nucleotide tRF-3b can regulate Ca2+ ion transport by interacting with mRNA ORAI2 or CACNG proteins and modulating the activity of CYP20A1 and GAS7, proteins associated with kidney diseases, such as kidney nephropathy, proteinuria and chronic kidney disease." (PMID 35409004, 2022).
colon adenocarcinoma (1 paper, 2021). "A cluster of 13 CpG loci (11 genes) were identified that displayed differential methylation in colon adenocarcinoma (COAD) (N = 289) compared to normal colon tissues (N = 38): ZNF671, TWIST1 (two CpG loci), TMEFF2, TM6SF1, GAS7, MAL, HIN1 (two CpG loci; SCGB3A1), COL6A2, AKR1B1, GPX7, ARHGEF7)." (PMID 34903270, 2021).
colon cancers (1 paper, 2015). "Like CRIPTO, TNS-1 and GAS-7, the other two genes in the associated regions present in the network, are both involved in breast and colon cancer." (PMID 25629528, 2015). "GAS-7 hypermethylation has been found in breast and colon cancers whereas increased expression has been detected in medulloblastoma." (PMID 25629528, 2015).
lymph-node metastasis (1 paper, 2018). "Clinical data and public domain data sets reveal that reduced GAS7 expression is associated with lymph-node metastasis and poor overall survival." (PMID 29706651, 2018). "The result indicated that lower GAS7 expressions were significantly correlated with positive lymph-node metastasis." (PMID 29706651, 2018).
meningioma (1 paper, 2013). A generally slow growing tumor attached to the dura mater. "Most of these genes were lowly expressed in both benign and malignant meningiomas; however, five genes (ADCY3, GAS7, LAG3, LRR32 and SPON2) showed a trend of elevated expression (>3 fold in mean values) in malignant meningiomas." (PMID 23349797, 2013).
osteoporosis (1 paper, 2013). A condition of reduced bone mass, with decreased cortical thickness and a decrease in the number and size of the trabeculae of cancellous bone (but normal chemical composition), resulting in increased fracture incidence. "In this review, we summarize the involvement of Gas7 in MSC-based osteogenesis and osteoporosis and describe the possible mechanisms responsible for the maintenance of cellular homeostasis in MSCs and osteoblasts." (PMID 23840221, 2013).
Wiskott-Aldrich syndrome (1 paper, 2023). Wiskott-Aldrich syndrome (WAS) is a primary immunodeficiency disease characterized by microthrombocytopenia, eczema, infections and an increased risk for autoimmune manifestations and malignancies. "The regulated GAS7 assembly was abolished by Wiskott-Aldrich syndrome mutations both in vitro and in cellular phagocytosis." (PMID 37126564, 2023).
tumor (19 papers, 2011 to 2025). "Results showed that GAS7 expression was associated with inhibition of tumor metastasis (p = 3.906e−07), RAI14 expression was associated with high pathological grade (p = 0.036) and advanced clinical stage (p = 0.046), and SLC2A6 expression was associated with high pathological grade (p = 9.835e−04)." (PMID 33312950, 2020). "Genes that were identified as markers of TAM2 in human ccRCC cells, including Fn1, F13a1 and Gas7 were more highly expressed in Mono-macrophage cluster 2 cells from tumours than from normal kidneys." (PMID 40473819, 2025). "Enhances miR-196a stability, inhibits GAS7 expression, reduces immune cell infiltration, facilitates tumor immune evasion, affecting the tumor microenvironment." (PMID 40740874, 2025). "Western blot assay showed that the GAS7 protein levels were also up-regulated in tumor tissues of Anti-miR-196a." (PMID 38370374, 2024). "In summary, we have shown that GAS7, a direct downstream target of miR-362-5p, can exert its tumor suppressive functions in THP-1 cells through regulation of PCNA, CDK4, cyclin D1, and p21." (PMID 31925702, 2020). "Consistent with the in vitro results, THP-1 tumor cells exhibited high expression of GAS7 protein and low expression of CDK4 after treatment with miR-362-5p inhibitor, which was notably reversed after treatment with miR-362-5p mimic." (PMID 31925702, 2020). "Potential tumor suppressor genes GAS7, RGS6, ADAM11 and FBXL2 are up-regulated in the lesser aggressive group L." (PMID 29844869, 2018). "In addition, we detect the level of miR-196a and GAS7 in tumor tissues and found that miR-196a is obviously downregulated and GAS7 is markedly up-regulated in anti-miR-196a group." (PMID 38370374, 2024). "Previous studies indicated that GAS7 acts as a tumor suppressor in human cancers." (PMID 34201353, 2021). "It is suggested that the downregulation of GAS7 results in high metastatic ability of tumor cells." (PMID 33968341, 2021). "GAS7 overexpression imitated the tumor suppressive effect of silenced miR-362-5p on THP-1 cells." (PMID 31925702, 2020). "In addition, GAS7 expression in NSCLC patients may be positively related with the infiltration of immune cell subsets in tumor microenvironment (TME)." (PMID 38370374, 2024). "Seven genes (CACNB2, IL34, CGNL1, CNTN3, GAS7, HOPX, and PBX1) regulated by miR-31-5p and miR-31-3p were identified as putative tumor suppressors." (PMID 34201353, 2021). "Furthermore, we found that the GAS7 expression was positively related to the infiltration of CD8 T cells, B cells, macrophages, CD4 T cells, neutrophils and Dendritic cells in the tumor microenvironment of NSCLC patients." (PMID 38370374, 2024). "These genes likely function as downstream effectors of STAT3 in GBM to regulate not only cell proliferation (e.g., GAS7, IGFBP2, MEOX2 and MXI1), and but also tumor-stroma interactions by modulating protein secretion (e.g., ANXA1, ARL4C, EMILIN1, EMP2, EXTL3 and PDIA4)." (PMID 29774125, 2018).
cancer (18 papers, 2006 to 2025). A tumor composed of atypical neoplastic, often pleomorphic cells that invade other tissues. "Spatial localization of GAS6 and GAS7 expressions within the GAS pathway revealed concentrated expression of these genes in regions populated by high-risk cancer cells." (PMID 41034991, 2025). "GAS7, as a growth arrest-specific gene, has been reported to hinder the progression of malignant tumours." (PMID 36908025, 2023). "Although hnRNP U associates with the WW domain of GAS7, little is known about the effect and the mechanism of this interaction between GAS7 and hnRNP U in cancer cells." (PMID 26506240, 2015). "Our experimental data also suggested that the METTL3/miR‐196a/GAS7 axis may be a promising therapeutic target for NSCLC or other cancers." (PMID 38370374, 2024). "In addition, qPCR confirmed that many NDD-related genes, such as CAMKMT, COX15, and GAS7 involved in neurodevelopment and cancer, were downregulated in the patients." (PMID 37664546, 2023). "We identified HBV integrations with high integration allele fractions in tumors in seven non-recurrent cancer-related genes, including GAS7, NSP, RSPO2, NRG1, PRDM16, ARID1B, and AFF1." (PMID 33557409, 2021). "Among these genes, 18 cancer driver genes showed a dual role associated with epigenetic changes, five of which were considered to be critical: SLC27A6, PDGFRA, GAS7, PLXNC1, and NRP2." (PMID 31900418, 2020). "The potential role of GAS-7 in cancer or apoptosis remains to be determined." (PMID 30713602, 2019). "Interestingly, OV S-model includes an isoform in the cancer driver GAS7." (PMID 27535130, 2016).
infection (2 papers, 2012 to 2025). The state of being infected such as from the introduction of a foreign agent such as serum, vaccine, antigenic substance or organism. "After 48 hours of infection, cells were harvested and Gas7 expression was quantified by Western blotting." (PMID 22662195, 2012).
GAS7 also shares sentences with these, for which no sentence is quoted: leukemia (11 papers); psychosis (2); Sepsis (2); acute leukemia (1); acute myocardial infarction (1); acute promyelocytic leukemia (1); anxiety disorder (1); Ataxia (1); autism (1); B-cell acute lymphoblastic leukemia (1); COVID-19 (1); exfoliation syndrome (1); gastric carcinoma (1); kidney diseases (1); kidney nephropathy (1); lung adenocarcinoma (1); lung squamous cell carcinoma (1); medulloblastoma (1); metastatic tumors (1); neurodevelopmental disorder (1); neurofibroma (1); oral lichen planus (1); pancreatic endocrine tumors (1); primary open-angle glaucoma (1); prostate carcinoma (1); psychiatric disorder (1); synucleinopathy (1); type 1 diabetes (1).